POLD1 (DNA polymerase delta 1, catalytic subunit)
Diseases named in the same sentence as POLD1 in open-access papers (continued):
Sharing a sentence is not in itself a finding about the gene and the disease.
melanoma (14 papers, 2017 to 2025). A malignant, usually aggressive tumor composed of atypical, neoplastic melanocytes. "In their analysis, they observed that high TMB was only associated with better survival in the case of MSI- or POLD (POLE or POLD1)-mutated tumors, or in cancers highly related to environmental carcinogens (head and neck, lung, and melanoma)." (PMID 37108755, 2023). "Thus, it appears that CTCFL mutations are often produced by underlying MSI or POLE or POLD1 defects in both cancers commonly associated with these defects (colorectal and endometrial) and in other cancers less commonly associated with them (melanoma)." (PMID 30275357, 2018). "The identified studies indicated that POLE and POLD1 mutations are biomarkers for immunotherapy across multiple cancer types, and BRAF mutation can improve antitumor activity of immunotherapy in melanoma." (PMID 34211853, 2021). "As expected, we found that (both primary and metastatic) melanomas were mainly characterized of signatures SBS7a/b (exposure to UV light), SBS1 (spontaneous deamination of 5-methylcytosine; clock-like), SBS5 (clock-like) and SBS10b (POLE/POLD1 mutations)." (PMID 36389735, 2022). "Of the two POLD1 variants identified (neither in ClinVar), p.Q411H (melanoma at 28 years and MSS CRC at 58 years) and p.Q684H (MSS CRC at 55 years), only the former resided within the exonuclease domain." (PMID 29212164, 2017). "Next-generation sequencing (NGS) (whole genome or exome) has facilitated further discovery of cancer susceptibility genes including RECQL, FANCM, FANCC, XRCC2, POT1, and BAP1 for breast and melanoma, and POLE, POLD1, and NTHL1 for CRC." (PMID 29212164, 2017). "However, the mechanism of POLD1 action in melanoma has not been explored." (PMID 40019657, 2025).
adenoma (11 papers, 2014 to 2024). A neoplasm arising from the epithelium. "We have observed, for the first time, that hypermutability in cancers or adenomas is associated with somatic loss of the wildtype POLD1 allele." (PMID 38658779, 2024). "Therefore, increases in SBS and ID mutation rates are associated with conversion from a normal crypt to an adenoma or cancer crypt in individuals with POLE or POLD1 germline mutations, a pattern similar to that observed in healthy individuals." (PMID 34594041, 2021). "Most colorectal polyps were tubular or tubulovillous adenomas, although nine POLE and five POLD1 variant heterozygotes also had hyperplastic polyps." (PMID 33948826, 2022). "Patients who carry EDMs in POLE or POLD1 show variable phenotypes: some have tens of adenomas that do not appear to progress rapidly to cancer, whereas others have a small number of large adenomas or early-onset carcinomas, thus resembling Lynch syndrome." (PMID 24583393, 2014). "The elevated mutation loads in adenoma and carcinoma crypts from POLE/POLD1 germline mutation carriers compared to normal intestinal crypts from each individual were also predominantly due to increased burdens of SBS10a and 10b (in POLE-mutant cases) and SBS10c and SBS10d (in POLD1-mutant cases)." (PMID 34594041, 2021). "Subsequent screening of 3,805 CRC patients revealed that these variants are relatively rare in patients with a positive family history of adenomas or CRC: POLE p.(Leu424Val) was found 12 times and POLD1 p.(Ser478Asn) only once." (PMID 30827058, 2019). "Other works analyzing AAP cohorts, such as Grover30 who analyzed MUTYH and APC in 4223 patients with 10 to 100 adenomas, or Stanich20 who also analyze POLD1 and POLE and other CRC genes in 2979 patients with 10 to 100 adenomas, showed similar clinical results." (PMID 31285513, 2019). "Twelve of 27 (44%) POLD1 variant heterozygotes developed CRC, none had prior adenoma removal and 5 had no reports of CRAs." (PMID 33948826, 2022). "The difference in frequency of CRCs and adenomas was not significantly different between POLE and POLD1 heterozygotes (Fisher’s exact test, CRC p = 0.12, CRA p = 0.19)." (PMID 33948826, 2022).
hepatocellular carcinoma (11 papers, 2013 to 2026). A malignant tumor that arises from hepatocytes. "POLD1 is highly expressed in various cancers, including bladder, breast, endometrial, colorectal, lung, and hepatocellular carcinoma, as evidenced by both clinical studies and TCGA database analyses However, its expression patterns yield paradoxical clinical outcomes depending on tumor context." (PMID 40661943, 2025). "AP-2α directly regulates transcription of critical DNA repair genes such as TOP2A, NUDT1, POLD1, and PARP1 in hepatocellular carcinoma, thereby facilitating repair of oxidized DNA lesions." (PMID 41373739, 2025). "The aim of the present study was to investigate the mechanism by which Smilax china L.-containing serum suppresses SMMC-7721 human hepatocellular carcinoma (HCC) cell growth as well as to determine its effect on the expression of DNA polymerase δ catalytic subunit gene 1 (POLD1)." (PMID 24137319, 2013). "Furthermore, hepatocellular carcinoma, the end-stage of NAFLD, displays higher POLD1 expression levels than normal liver tissues, and this is associated with a poor prognosis." (PMID 37822923, 2023). "However, the effect of POLD1 in hepatocellular carcinoma (HCC) is not well-understood." (PMID 35189839, 2022).
glioma (10 papers, 2019 to 2025). A benign or malignant brain and spinal cord tumor that arises from glial cells (astrocytes, oligodendrocytes, ependymal cells). "While six of the nine different POLE and POLD1 germline missense variants identified here in glioma patients affect amino acids located within or close to the exonuclease domain, three variants affect amino acids in other parts of POLE." (PMID 37990341, 2023). "Rare heterozygous POLE/POLD1 missense variants predicted to be deleterious were identified in glioma patients from 10 (16%) families, co-segregating with the tumor phenotype in families with available DNA from several tumor patients." (PMID 37990341, 2023). "Our data provide evidence that deleterious POLE and POLD1 germline missense variants predispose to gliomas, which should be considered a part of the PPAP tumor spectrum, and increase the risk of spinal metastasis development." (PMID 37990341, 2023). "In 13/15 (87%) gliomas from patients carrying POLE/POLD1 variants, features of defective polymerase proofreading, e.g. hypermutation, POLE/POLD1-associated mutational signatures, multinucleated cells, and increased intratumoral T cell response, were observed." (PMID 37990341, 2023). "In this study, we highlight the role of rare heterozygous germline variants in POLE and POLD1 in glioma predisposition and the risk of developing spinal metastases." (PMID 37990341, 2023). "Yet, the clinical significance of POLD1 mutations and changes in the POLD1 protein level in central nervous system tumors is not fully understood." (PMID 36980791, 2023). "The finding of a somatic pathogenic variant in POLD1 in the high-grade glioma of this patient suggested the hypermutant nature of the tumor that characterizes brain malignancies developed in CMMRD." (PMID 33924881, 2021). "Consistent with our finding of enlarged nuclei or multinucleated cells in 6/15 (40%) gliomas from patients with POLE/POLD1 germline variants, multinucleated giant or bizarre cells, features of giant cell glioblastoma, were previously observed in high-grade gliomas harboring somatic POLE variants." (PMID 37990341, 2023). "Data compiled here suggest that glioma patients carrying POLE/POLD1 variants may be recognized by cutaneous manifestations, e.g. café-au-lait macules, and benefit from surveillance colonoscopy." (PMID 37990341, 2023). "Features of defective polymerase proofreading in most gliomas from patients carrying POLE/POLD1 variants suggest that these tumors may be susceptible to ICIs." (PMID 37990341, 2023). "As defects in polymerase proofreading have been associated with the formation of multinucleated giant cells, hematoxylin and eosin stained sections of 15 gliomas from 11 patients with rare POLE/POLD1 variants were evaluated by an experienced neuropathologist (CH)." (PMID 37990341, 2023). "Our data provide evidence that rare POLE/POLD1 germline variants predispose to gliomas that may be susceptible to ICIs." (PMID 37990341, 2023). "While DNA mismatch repair (MMR) deficiency-associated mutational signatures SBS6, SBS15, SBS21, or SBS26 were identified in 13 of 14 (93%) glioma DNAs from 10 patients with rare POLE/POLD1 variants, a substantial (> 50%) contribution was detected in only 5 of 14 (36%) gliomas." (PMID 37990341, 2023). "Therefore, all POLE/POLD1 germline variant carriers with gliomas showing features of defective polymerase proofreading, i.e. 87% of gliomas analyzed here, may benefit from immunotherapy." (PMID 37990341, 2023). "A mean TMB of 13.9 mutations per megabase (mut/Mb) was identified in 14 glioma DNAs from 10 patients with rare POLE/POLD1 variants, with each TMB value higher than 2.6 mut/Mb, the median TMB in a study of 10,294 gliomas." (PMID 37990341, 2023). "Additionally, POLD1 expression in this heterogeneous group of neoplasms was only described in 1p19q co-deleted lower-grade gliomas." (PMID 36980791, 2023).
glioma (continued). "In the CNS LS-related tumor group, 6 glioma samples (PLS041, PLS046, PLS124, PLS143, PLS185, PLS228) had a TMB greater than 300 but were MSS, and we found each patient harboring mutations in the DNA polymerase genes, POLE or POLD1, which are associated with a hypermutated phenotype." (PMID 41261115, 2025). "Taken together, seven different rare POLE and two different rare POLD1 variants, heterozygous and predicted to be deleterious, were detected in WES datasets of leukocyte DNA of a total of 11 glioma patients from 10 of 61 (16%) tumor families, including the glioma patients from family Fam011." (PMID 37990341, 2023).
Lynch syndrome (10 papers, 2014 to 2026). An autosomal dominant hereditary neoplastic syndrome characterized by the development of colorectal carcinoma and a high risk of developing endometrial carcinoma, gastric carcinoma, ovarian carcinoma, renal pelvis carcinoma, and small intestinal carcinoma. "Among the cases with MSI, the majority of them are LS cases with a mutation in DNA repair (MMR) genes detected, although MSI may also be observed in sporadic CRC due to somatic alteration in MMR genes or cases of Lynch-like syndrome caused by mutation of other genes (POLE/POLD1)." (PMID 36553592, 2022). "We interpret the case as a patient with Lynch syndrome with two secondary, non-pathogenic POLE mutations, not included in the list of mutations detected by the Modaplex POLE/POLD1 Mutation Analysis Kit." (PMID 37874375, 2023).
hereditary cancer (9 papers, 2014 to 2023). Malignant neoplasms occurring in families at a rate greater than that expected by chance and caused by germline mutations in a specific gene. "The frequency of rare ED missense variants—including pathogenic and VUS—in POLE and POLD1 in hereditary cancer was 0.39% (9/2309)." (PMID 32792570, 2020). "The tumor spectrum and prevalence of POLE and POLD1 variants in hereditary cancer are evaluated in this study." (PMID 32792570, 2020). "POLD1 has been recently recognized as hereditary cancer-predisposing genes." (PMID 36717774, 2023). "While germline POLD1 mutations might be related to familial cancers, the oncogenic value of somatic POLD1 exonuclease domain mutations (EDMs, also referred to proofreading domain mutations) is still controversial." (PMID 32859741, 2020). "In addition, mutations in the proofreading domain of POLD1 have been identified as the root cause of some hereditary cancers and these mutations may affect treatment management." (PMID 34868924, 2021). "POLE and POLD1 were sequenced in 2813 unrelated probands referred for genetic counseling (2309 hereditary cancer patients subjected to a multigene panel, and 504 patients selected based on phenotypic characteristics)." (PMID 32792570, 2020). "POLD1 appears to be a biomarker for predicting prognosis in cases of hereditary cancer." (PMID 36732815, 2023).
colorectal polyps (8 papers, 2015 to 2025). "Germline mutations in POLE and POLD1 have been shown to predispose patients to multiple colorectal polyps and a wide range of neoplasms." (PMID 34868924, 2021). "Here, we screened the exonuclease domain of POLE and POLD1 to detect causative variants in 332 index patients with multiple colorectal polyps." (PMID 30827058, 2019). "Pathogenic mutations involving the proofreading domains of POLE and POLD1 are widely known to be associated with colorectal polyposis and cancer." (PMID 31866764, 2019). "We recommend that screenings of POLE and POLD1 should still be considered, although pathogenic variants in POLE and POLD1 probably occur at a low frequency in patients with multiple colorectal polyps." (PMID 30827058, 2019). "To discover the underlying genetic causes of multiple colorectal polyps and CRC in genetically unexplained cases, we aimed to screen the exonuclease domains of POLE and POLD1 in this group of patients." (PMID 30827058, 2019). "While predisposing variants in genes such as NTHL1, MSH3, POLE, POLD1, DSC2, and PIEZO1 have been associated with colorectal polyposis, they do not fully mimic the classical FAP phenotype." (PMID 41204315, 2025). "Using a custom next‐generation sequencing panel, we sequenced the exonuclease domains of POLE and POLD1 in 332 index patients diagnosed with multiple colorectal polyps without germline alteration in colorectal polyposis predisposing genes." (PMID 30827058, 2019).
gastric cancer (8 papers, 2013 to 2025). A primary or metastatic malignant neoplasm involving the stomach. "On the other hand, the high expression of POLD1 gene is predicted to be associated with more gastric cancer and lung cancer patients at risk (less survival rate)." (PMID 35620275, 2022). "Based on the results from Kaplan-Meier plot analysis, we associated the deregulation of the POLD1 gene with the survival of the patients with lung and gastric cancer." (PMID 35620275, 2022). "The fraction of A→G mutations was increased in stomach cancers with concurrent mutations on POLD1 and POLE genes." (PMID 28582771, 2017). "Recent studies have shown that genetic mutations in the POLD1 gene are related to lymphoma, liver, colon and gastric cancer." (PMID 24137319, 2013). "Among the most highly significant genes were all those previously reported in the context of the hypermutator phenotype of gastric cancer, including POLD1 (p-value < 10−11), POLE, KMT2C, KMT2A (p-value < 10−8), and MLH1 (p-value < 10−4)." (PMID 41301688, 2025). "Twenty-four hyper-mutated tumors were identified only in colorectal and gastric cancers, with a significant enrichment of mutations in the polymerase genes (POLE, POLD1, and POLH) and mismatch repair (MMR) genes." (PMID 34594355, 2021). "Future studies can examine the POLQ knockdown in stomach cancer cell lines with concurrent defects of POLD1 and POLE." (PMID 28582771, 2017). "Although the result of Kaplan-Meier plot analysis indicated that the POLD1 deregulation can be treated as a significant prognostic tool in detecting the lung and gastric cancers in patients, its role is limited in case of the breast and ovarian cancer detection." (PMID 35620275, 2022).
bladder cancer (7 papers, 2022 to 2025). "Here, we determine that POLD1 has a pro-carcinogenic role in bladder cancer (BLCA) and is associated to the malignancy and prognosis of BLCA." (PMID 37105989, 2023). "In bladder cancer, POLD1 stabilizes MYC by inhibiting its degradation via FBXW7, promoting proliferation and metastasis." (PMID 40661943, 2025). "In bladder cancer research, it has been found that DNA polymerase delta 1 (POLD1) is highly expressed in bladder cancer tissues compared to adjacent tissues." (PMID 39768855, 2024). "Further experiments conducted in vitro and in vivo have demonstrated that POLD1 promotes the proliferation and metastasis of bladder cancer by stabilizing MYC." (PMID 39768855, 2024). "POLD1 also frequently co-occurs with oncogenic drivers like APC, BRCA2, and MYC, notably in colorectal and bladder cancers." (PMID 40661943, 2025). "In bladder cancer, POLD1’s stabilization of MYC suggests that MYC inhibitors (e.g., KJ-Pyr-9) could disrupt this axis, while miR-155 agonists might suppress POLD1 expression by downregulating FOXO3a, reducing replication fidelity in tumor cells." (PMID 40661943, 2025). "POLD1 stabilizes MYC and leads to faster cell growth and metastasis in bladder cancer cells." (PMID 39910288, 2025). "POLD1, one of the four subunits of DNA polymerase δ (POLD1, POLD2, POLD3, and POLD4) and which is upregulated in many tumors including bladder cancer, has been shown to directly bind to MB1 domain of MYC competitively with Fbw7, preventing Fbw7-mediated MYC ubiquitination and degradation." (PMID 39031286, 2024). "The subsequently elevated levels of MYC increases the transcription of POLD1 forming a positive feedback loop, and it was suggested that this non-enzymatic function of POLD1 may play a role in the tumorigenesis and progression of bladder cancer." (PMID 39031286, 2024). "Here, the authors report a non-canonical role of POLD1 wherein it stabilises MYC protein, creating a positive feedback loop with POLD1 expression and driving bladder cancer progression and metastasis." (PMID 37105989, 2023).
Familial adenomatous polyposis (7 papers, 2016 to 2025). Familial adenomatous polyposis (FAP) is characterized by the development of hundreds to thousands of adenomas in the rectum and colon during the second decade of life. "The POLD1 mutation c.1379 T > G;p.Leu460Arg in a patient with colorectal adenomatous polyposis and renal cancer is located in the vicinity of the known hotspot mutation c.1433G > A;p.Ser478Asn." (PMID 30680046, 2019). "Furthermore, a POLD1 missense variant in the proofreading domain of the protein (c.1379 T > G;p.Leu460Arg) was identified in a patient with colorectal adenomatous polyposis and papillary renal cancer (ID 38569)." (PMID 30680046, 2019). "The main autosomal dominant adenomatous polyposis syndromes include familial adenomatous polyposis (FAP) and polymerase proofreading-associated polyposis (PPAP), caused by germline PVs in APC and the POLE and POLD1 genes, respectively." (PMID 40237887, 2025). "First, we searched for deleterious variants in the genes associated with adenomatous polyposis of the colon (APC, MUTYH, NTHL1, POLD1, and POLE)." (PMID 27217144, 2016). "People with polyposis could have a genetic basis with germline mutations in polyposis-related genes, such as the APC gene, resulting in familial adenomatous polyposis (FAP), MUTYH-associated polyposis (MAP), or, rarely, in other genes such as AXIN2, GREM1, NTHL1, POLE, POLD1, or MSH3." (PMID 40095498, 2025).